ELF4 (E74 like ETS transcription factor 4)
Diseases named in the same sentence as ELF4 in open-access papers (continued):
Sharing a sentence is not in itself a finding about the gene and the disease.
tumor (continued). "Collectively these results show that high-ELF4 tumours, compared to the low-ELF4 tumours, tend to be of a higher-grade, afflict a significantly older patient population and have a significantly higher mutation burden." (PMID 33836003, 2021). "We examined the relationship between the mRNA expression level ELF4 in thousands of primary tumours and cancer cell lines of 32 different cancer types and both the clinical outcomes and likely anti-cancer drug responses." (PMID 33836003, 2021). "Our analyses indicate that high-ELF4 tumours are typical among the elderly, and these also tend to have a higher mutation load." (PMID 33836003, 2021). "Here, for 19 out of 32 cancer types, we found that the overall survival periods were shorter for patients with high-ELF4 tumours than those with low-ELF4 tumours." (PMID 33836003, 2021). "Here, we investigate the mRNA expression variations of ELF4 across pan-cancer TCGA tumours to identify the changes that have meaningful clinical value." (PMID 33836003, 2021). "Further, we find that tumours that express high ELF4 mRNA levels tend to be of a higher-grade, afflict a significantly older patient population and have a significantly higher mutation burden." (PMID 33836003, 2021). "Correspondingly, we observed that the disease-free survival (DFS) periods were significantly shorter (log-rank test; p = 1.07 x 10−07) for the patients with high-ELF4 tumours than they were for the patients with low-ELF4 tumours." (PMID 33836003, 2021). "These and other recent studies have also generated a new appreciation of how aberrant ELF4 influences cancer development, the anti-cancer drug response of tumours, and the disease treatment outcomes." (PMID 33836003, 2021). "Next, we compared the duration of the overall survival periods between patients with tumours that expressed high and low levels of ELF4 across the 32 cancers." (PMID 33836003, 2021). "Our results suggest that the tumour’s ELF4 expression levels are directly correlated with the aggressiveness of cancer." (PMID 33836003, 2021). "Suitably, by probing the drug response profiles of cancer cell lines, we showed that high-ELF4 tumours and low-ELF4 tumours perhaps respond differently to many anti-cancer drugs." (PMID 33836003, 2021). "Of note, the tumor suppressor candidate ELF4 facilitates entrance to the cell cycle of quiescent hematopoietic stem cells." (PMID 20500816, 2010). "Furthermore, serving as a double-edged sword in cancer, ELF4 exhibits both tumor-suppressing and tumor-promoting effects." (PMID 40083328, 2025). "TISIDB analysis showed a positive correlation between ELF4 expression and tumor grade." (PMID 41287970, 2025). "A recent study further confirmed that ELF4 functions as a tumor suppressor gene in various cancers." (PMID 41300273, 2025). "ELF4 acts as a tumor suppressor and is inactivated in multiple cancers." (PMID 40083328, 2025). "As a potential tumor suppressor, ELF4 is down-regulated by methylation in multiple cancers." (PMID 40083328, 2025). "In addition to the tumor invasive role, enrichment analysis revealed the overexpressed ELF4 was involved in the immune regulation, characterized by the elevated activity of Il6/Jak/Stat3 signaling, interferon alpha (IFN-α) response, and IL2/Stat5 signaling." (PMID 39132148, 2024). "ELF4 can augment cancer stemness and further promote tumor growth and metastasis in ESCC." (PMID 37674363, 2023). "High ELF4 expression is shown to be related to worse disease outcomes in several cancers, including PC, although observations exist in accordance with its both oncogenic and tumor suppressor roles in different cancer types." (PMID 36386839, 2022). "Whereas ELF4 is virtually undruggable, we could employ a network analysis approach to identify the upstream regulatory proteins that could be targeted to treat tumours that overexpress ELF4." (PMID 33836003, 2021).
tumor (continued). "Furthermore, we explored the expression of ELF4 across tumour types across the two pan-cancer groups (high-ELF4 and low-ELF4)." (PMID 33836003, 2021). "Here, our results indicate that the expression of ELF4 does not only detectably impact the clinical outcomes of the patients but might also be a relevant variable to predict the response of tumours to various anti-cancer agents." (PMID 33836003, 2021). "We used the z-score normalisation methods to segregate the patient’s tumours into two groups of cancers: those cancers with higher levels of ELF4 (which we named as the "high-ELF4 tumours"; 3,887 samples) and those with a lower level of ELF4 ("low-ELF4 tumours"; 5,463 samples; see Methods sections)." (PMID 33836003, 2021). "Here, using ELF4 mRNA expression data of 9,350 samples from the Cancer Genome Atlas pan-cancer project, we identify two groups of patient’s tumours: those that expressed high ELF4 transcripts and those that expressed low ELF4 transcripts across 32 different human cancers." (PMID 33836003, 2021). "We found that the median age of the patients with tumours that expressed higher ELF4 was significantly higher (median = 63 years) compared to that of patients with tumours that expressed lower levels of ELF4 (median = 58 years), Wilcoxon rank-sum test (Z = 119.2, p < 1 x 10−300)." (PMID 33836003, 2021). "However, there is no solid evidence of ELF4 acting as a tumor suppressor gene and the ELF4 mutations have not yet been found in human cancers." (PMID 40083328, 2025). "Tumor heterogeneity may contribute to the differing expression and effects of ELF4." (PMID 40083328, 2025). "To further explore the ELF4 potential in regulating tumor immune microenvironment, we deeply examine the correlation between ELF4 expression and various tumor-infiltrating immune cells across different tumor types using the Tumor Immune Estimation Resource (TIMER) 2.0 database analysis." (PMID 40083328, 2025). "Thus, the function of ELF4 in tumor immunity is a subject that needs clarification." (PMID 40083328, 2025). "Importantly, across all analyzed cancers, ELF4 expression is positively correlated with malignant cells, which hints that ELF4 may affect tumor malignant features positively." (PMID 40083328, 2025). "Here, the categories of the cancer cell lines that have ELF4 mRNA levels that correspond to those of cancer cells from the patient groups could be used to examine how ELF4 levels in the patient’s tumour cells are likely to influence the effectiveness of particular anti-cancer drugs." (PMID 33836003, 2021). "Further, our analyses of the dose-response profiles of well-characterised cell lines have revealed that the expression levels of ELF4 in tumours may be related to the varied responses of the cancer cell to drug perturbation, a finding that could help shape precision medicine." (PMID 33836003, 2021). "Besides enabling the identification and selection of the most suitable anti-cancer drugs to treat a tumour with different ELF4 expression signatures, a multiscale understanding of ELF4 across different cancer types will likely yield better prediction of disease outcome." (PMID 33836003, 2021). "In human non-small cell lung carcinoma A549 cells, ELF4 inhibits the expression of matrix metallopeptidase 9 (MMP9) and IL8 by reducing their promoter activities, thereby repressing tumor growth and invasiveness." (PMID 40083328, 2025). "Herein, we first explored the expression of ELF4 in ESCC samples and delineated its relationship with tumor progression and prognosis." (PMID 37674363, 2023). "Knockout of ELF4 in macrophages dramatically enhanced the antitumor effect of PD1 blockade and inhibited tumor growth." (PMID 36209117, 2022).
tumor (continued). "We showed that clinically relevant subtypes of patient tumours, across many cancer types, could be achieved by simply dividing the tumours into two categories based entirely on the expression of ELF4: those tumours which express high ELF4 levels and those that express low ELF4 levels." (PMID 33836003, 2021). "There is no doubt that further research on ELF4 in physiological immunity, pathological immunity, or tumor immunity is an inspiring and promising direction." (PMID 40083328, 2025). "Furthermore, we analyzed the correlation between ELF4 expression and the TME at the single-cell level using the Tumor Immune Single-cell Hub (TISCH) database." (PMID 40083328, 2025). "Interestingly, we have identified several transcription factors like TRPS1, NFAT5, FoxF2, ELF4, RLF etc. which haven’t previously been reported to be involved in PDAC but shown to induce EMT, angiogenesis or proliferation of tumours in other organs." (PMID 31795960, 2019).
cancer (14 papers, 2017 to 2025). A tumor composed of atypical neoplastic, often pleomorphic cells that invade other tissues. "Advancements in multiomics and bioinformatics have helped to explicate how changes in ELF4 expression in human cancers are associated with disease outcomes and drug response in cancer cells." (PMID 41300273, 2025). "ELF4 (E74-like factor 4) is a transcription factor, dysregulation of which has been associated with carcinogenesis and cancer development." (PMID 39132148, 2024). "Previous findings demonstrate that ELF4 is implicated in the sensitivity to anti-cancer drugs/compounds at the pan-cancer level." (PMID 39132148, 2024). "High ELF4 expression in human cancers is associated with worse disease outcomes and increased resistance to anticancer drugs." (PMID 36158120, 2022). "The general feature of ELF4 is critically associated with cellular processes, such as immune response, osteogenesis, and cancer cell quiescence." (PMID 36158120, 2022). "Overall, these findings show that while the expression of ELF4 is associated with increased disease aggressiveness of most cancer types, there are some exceptions." (PMID 33836003, 2021). "Here, these findings expose an association between the expression levels of ELF4 and the clinical outcomes across various cancer types." (PMID 33836003, 2021). "By linking this information with the drug response profiles from the GDSC, we also investigate variations in the response of cancer cell types that are associated with ELF4 mRNA levels." (PMID 33836003, 2021). "Additionally, the functional analysis of ELF4 was systemically explored, and cancer-related and immune-associated processes and pathways were correlated to ELF4 expression." (PMID 39132148, 2024). "Additionally, ELF4 suppression mediated by DNA methyltransferase 1 (DNMT1) methylation of its promoter drives the transformation of ulcerative colitis to colitis-associated cancer." (PMID 40083328, 2025). "Mounting evidence suggests ELF4 drives tumorigenesis and cancer progression through diverse mechanisms." (PMID 41287970, 2025). "Growing clinical studies have shown that ELF4 is significantly correlated with poor prognosis in cancer, suggesting its potential for early diagnoses and prognosis assessments." (PMID 40083328, 2025). "Genomic and biochemical research has demonstrated that ELF4 is a critical transcriptional factor in regulating physiological cellular behavior and plays a dual regulatory role in cancer." (PMID 40083328, 2025). "Despite significant progress, little is known about several other TFs, including ELF4, and how they help form the carcinogenic process in cancer cells." (PMID 41300273, 2025). "While abnormal ETS transcription factor expression influences biological processes in various malignant tumors, the regulatory mechanisms and clinical significance of ELF4 in EC remain poorly understood." (PMID 41287970, 2025). "From a cellular perspective, ELF4 expression is mainly associated with CD8+ T cells, monocytes/macrophages, and malignant cells in most cancer types." (PMID 40083328, 2025). "Based on bioinformatics analysis, cancers with elevated ELF4 expression are correlated with a higher grade, older patients, and a greater mutation burden." (PMID 40083328, 2025). "The correlation analysis was performed between ELF4 expression and immune checkpoints as well as the cancer-immunity cycle." (PMID 39132148, 2024). "There is evidence that ELF4 plays an important role in pathological processes, such as the regulation of cell differentiation and cell cycle in cancers." (PMID 39132148, 2024). "Clearly, high ELF4 expression was positively related to several immune checkpoints and negatively correlated with the majority of the cancer-immunity cycle." (PMID 39132148, 2024). "There was a strong possibility that ELF4 augmented ESCC cancer stem-like properties and further accelerated ESCC progression by transcriptionally regulating the expression of FUT9." (PMID 37674363, 2023).
cancer (continued). "In summary, our study demonstrated that ELF4 is a critical transcription factor that affects cancer stemness in ESCC." (PMID 37674363, 2023). "We also demonstrated that inhibition of ELF4 significantly reduced the cancer-promoting capacity of the ELF4-FUT9 axisin vitro and its oncogenicityin vivo." (PMID 37674363, 2023). "Considering that ELF4 was reported to affect cancer stemness in many cancers, we performed relevantin vitro andin vivo assays." (PMID 37674363, 2023). "Many previous studies have reported that ELF4 plays an important role in the immune response, osteogenesis, adipogenesis, cancer biology, and stem cell quiescence." (PMID 37674363, 2023). "ELF4, one of the ETS transcription factors, has been implicated in the pathogenesis and progression of various types of cancers." (PMID 37674363, 2023). "In cancer stem cells, regulation of the G1/S transition depends on the level of ELF4, a short-lived protein that regulates the cell cycle by being phosphorylated and ubiquitinated to control its expression level." (PMID 35928113, 2022). "From the GDSC database, we collected the dose-response of 612 cancer cell lines to 397 small molecule inhibitors, and their ELF4 mRNA expression levels from the CCLE database." (PMID 33836003, 2021). "To this end, we performed a bioinformatics analysis to facilitate a detailed understanding of how the expression variations of ELF4 in human cancers are related to disease outcomes and the cancer cell drug responses." (PMID 33836003, 2021). "Our current understanding of ELF4 and other cancer genes has largely been facilitated by large cancer profiling projects such as The Cancer Genome Atlas (TCGA) and the International Cancer Genome Consortium." (PMID 33836003, 2021). "Despite significant progress made, little is known about several other transcription factors, including ELF4, and how they help shape the oncogenic processes in cancer cells." (PMID 33836003, 2021). "We obtained and analysed a TCGA pan-cancer dataset comprising the mRNA expression levels of the ELF4 gene and comprehensively deidentified clinical information." (PMID 33836003, 2021). "Others have studied ELF4 in the context of tumorigenesis in cancers of the skin, breast and prostate." (PMID 33836003, 2021). "Our data demonstrate that TRIB3 positively regulates the cancer stem-cell activity and in vivo tumorigenicity of EC cells by modulating β-catenin signaling through directly interacting with the ELF4 transcription factor." (PMID 33334065, 2020). "In two transplantation lines (descending from C25 and E31) we observed the occurrence of new mutations in genes described as cancer drivers in COSMIC-CGC database, which are Rhoh, Npm1, Elf4, Ikbkb, and Nutm1." (PMID 30262843, 2019). "Many mutated genes from transplanted tumors encode proteins important for cell adhesion and transcription, among them the COSMIC-CGC cancer drivers Npm1, Nutm1, and Elf4." (PMID 30262843, 2019). "We compared the function of ELF2 isoforms ELF2A and ELF2B with other ELF subfamily proteins ELF1 and ELF4 in primary and cancer cell lines using proliferation, colony-forming, cell cycle, and apoptosis assays." (PMID 28351373, 2017). "Additionally, in murine cancer models, ELF4 is activated and serves as an inserted site for retroviral mutagenesis." (PMID 40083328, 2025). "A study revealed that 32 different human cancers could be divided into tumors expressing high ELF4 transcripts and tumors expressing low ELF4, and patients in the two groups were associated with different clinical outcomes." (PMID 41300273, 2025). "In most tumors, ELF4 expression has a positive correlation with macrophages (M1 and M2), monocytes, neutrophils, CD4+ T cells, CD8+ T cells, regulatory T cells, myeloid dendritic cells, endothelial cells, and cancer-associated fibroblasts." (PMID 40083328, 2025).